DPYD (dihydropyrimidine dehydrogenase)
Diseases named in the same sentence as DPYD in open-access papers (continued):
Sharing a sentence is not in itself a finding about the gene and the disease.
skin cutaneous melanoma (1 paper, 2018). "A cancer systems biology analysis of skin cutaneous melanoma broughtforward a new master regulator and diagnostic target in cancer metabolism.Somatic mutations of DPYD have the ability to reconfigure and activatepyrimidine metabolism promoting rapid cellular proliferation and metastaticprogression." (PMID 29615030, 2018).
squamous cell carcinoma (1 paper, 2022). A carcinoma arising from squamous epithelial cells. "In the present study, the ALDH2 (rs568781254) or DPYD variants (rs190771411 and rs200562975) were associated with an increased risk of squamous cell carcinoma patients compared to adenocarcinoma." (PMID 36289279, 2022). "Two variants of DPYD (rs190771411 and rs200562975) and a variant of ALDH2 (rs568781254) were associated with an increased risk of squamous cell carcinoma compared to adenocarcinoma in the dominant model (P < 0.05)." (PMID 36289279, 2022). "However, due to the low frequency of the minor allele of the variants (MAF of 0.0029 for ALDH2 and MAF of 0.0014 for DPYD), these were not large enough to detect an association with squamous cell carcinoma." (PMID 36289279, 2022).
urothelial carcinoma (1 paper, 2012). A malignant neoplasm derived from the transitional epithelium of the urinary tract (urinary bladder, ureter, urethra, or renal pelvis). "Recently, S-1, a novel 5-fluorouracil (5-FU)-based agent containing the strong dihydropyrimidine dehydrogenase (DPD) inhibitor, 5-chloro-2,4-dihydropyrimidine (CDHP) has been clinically used to treat various non-urothelial carcinomas (UC)." (PMID 22998564, 2012).
cancer (97 papers, 1997 to 2026). A tumor composed of atypical neoplastic, often pleomorphic cells that invade other tissues. "This study will determine the prevalence of DPYD gene variant status in Australia and its impact on FP-induced toxicity among Australians with cancer." (PMID 39516829, 2024). "Pre-treatment genotyping of four well-characterized toxicity risk-variants in the dihydropyrimidine dehydrogenase gene (DPYD) has been widely implemented in Europe to prevent serious adverse effects in cancer patients treated with fluoropyrimidines." (PMID 39062841, 2024). "Another example is testing for gene variants in dihydropyrimidine dehydrogenase (DYPD) before starting cancer treatment with fluorouracil given by injection or infusion." (PMID 39640415, 2024). "We present data on cancer chemotherapy-related pharmacogene variant frequencies in DPYD, UGT1A1, TPMT, NUDT15, and ABCB1 within the Chilean population, offering insights for the strategic implementation of pharmacogenetic testing." (PMID 38675222, 2024). "The aim of the present study was to analyze prevalence of DPYD rs3918290, rs55886062, rs67376798, rs75017182, and, additionally, rs1801160 variants, and assess their association with FP-induced toxicity in Greek cancer patients." (PMID 37781702, 2023). "Our results identified many novel variants located in essential genes to cancer (DPYD, TYMS, MTHFT, and GSTT1), infectious diseases (IFNL4), and psychiatric treatments (CYP2D6)." (PMID 35743738, 2022). "Eleven distinct IRAVs were identified in DPYD, mutations of which are implicated to increased risk of toxicity in cancer patients receiving 5-fluorouracil chemotherapy." (PMID 36175409, 2022). "Deficiency of dihydropyrimidine dehydrogenase (DPD), encoded by the DPYD gene, is associated with severe toxicity induced by the anti-cancer drug 5-Fluorouracil (5-FU)." (PMID 36430399, 2022). "The DPYD gene encodes a protein that is active in the catabolic pathway of 5-fluorouracil and DPYD mutations result in an increased risk of toxicity in cancer patients receiving 5-fluorouracil chemotherapy." (PMID 34026625, 2021). "In this work, we compared genetic variants, protein activity and blood DPYD mRNA expression in 41 cancer patients receiving fluoropyrimidine-based treatment." (PMID 34442436, 2021). "Although more than 160 polymorphisms in DPYD gene have been identified to date, data derived from Chinese cancer patients is very limited." (PMID 29340111, 2017). "Cancer patients carrying mutations in the dihydropyrimidine dehydrogenase gene (DPYD) have a high risk to develop severe drug-adverse effects following fluoropyrimidine drugs administration." (PMID 26801900, 2016). "We also need to elucidate the molecular mechanisms underlying the confounding effects of ERCC1 and DPYD gene expression in cancer cells." (PMID 26372896, 2015). "In an in vivo study in a small series of clinical samples from DPD-deficient volunteers and DPD-deficient cancer patients, Ezzeldin and colleagues confirmed that methylation of the DPYD promoter region is associated with down-regulation of DPD activity." (PMID 25906475, 2015). "Cancer patients carrying mutations in the dihydropyrimidine dehydrogenase gene (DPYD) have a high risk to experience severe drug-adverse effects following chemotherapy with fluoropyrimidine drugs such as 5-fluorouracil (5-FU) or capecitabine." (PMID 19104657, 2008). "Genetic deficiency of DPYD enzyme (gene U09178) results in an error in pyrimidine metabolism associated with thymine-uraciluria and an increased risk of toxicity in cancer patients receiving 5-flourouracil chemotherapy." (PMID 17316436, 2007). "Accordingly, it can be expected that at least a few different miRNAs regulate the levels of the proteins encoded by TYMS and DPYD, and that altering the levels of these miRNAs may also contribute to reducing the sensitivity of cancer cells to 5FU." (PMID 35922756, 2022).
cancer (continued). "Single nucleotide variants in DPYD have been linked to increased risk of severe toxicity following fluorouracil treatment in European and Asian cancer patient cohorts, and a variant specific to African Americans (compared to European Americans) was found to reduce DPD activity." (PMID 33767731, 2021). "DPYD deficiency has wide-ranging implications, and genetic variation in DPYD is associated with the risk of severe toxic reactions to fluoropyrimidines, which are used to treat cancer." (PMID 32127447, 2020). "5-FU causes GI-tract toxicities that may be serious and are occasionally lethal, particularly in cancer patients deficient in 5-FU catabolism due to polymorphisms in DPYD." (PMID 32575843, 2020). "A similar case is the one of dihydropyrimidine dehydrogenase (DPD) deficiency, which leads to increased toxicity in case of treatment with 5-fluorouracil or capecitabine (two widely used drugs in the treatment of various cancers)." (PMID 35582141, 2019). "Variable expression of DPYD and genetic polymorphisms in the DPYD gene have been linked to a high intra- and inter-patient variability in the plasma levels of 5-FU with associated toxicity and cancer drug resistance." (PMID 28851987, 2017). "Since about 80% of 5-FU is catabolized by dihydropyrimidine dehydrogenase (DPYD), the initial and rate-limiting enzyme of pyrimidine catabolism, only a small part of the 5-FU can inhibit thymidylate synthase (TS) so as to cause cancer cell death via thymineless death." (PMID 26457704, 2015). "Genotyping of four variants in DPYD gene that were found to be associated with 5-FU toxicity in South Asian population has been made available as an affordable diagnostic assay for testing cancer patients before administering the drug to prevent adverse reactions." (PMID 31554517, 2019). "In recent years, assessing dihydropyrimidine dehydrogenase (DPD) activity has become crucial for cancer patients undergoing 5-fluorouracil (5FU)-based chemotherapy due to the life-threatening toxicity associated with reduced DPD function." (PMID 40072607, 2025). "Deoxyribonucleic acid was prospectively obtained from 150 cancer patients and genotyped for DPYD*2A, *13, c.2846A>T, and Hap 3B." (PMID 37108974, 2023). "Cancer cells can become immune to this drug mainly by increasing 5-FU catabolism by dihydropyrimidine dehydrogenase (DPD) or by scaling the rate of dTMP biosynthesis." (PMID 33804620, 2021). "The dimeric dihydropyrimidine dehydrogenase (DPD), metalloenzyme, an adjunct anti-cancer drug target, contains highly specialized 4 × Fe2+4S2−4 clusters per chain." (PMID 34069161, 2021). "For example, dihydropyrimidine dehydrogenase (DPD) was an enzyme involved in the detoxification of 5-fluorouracil, a crucial anti-cancer agent." (PMID 33352764, 2020). "5-fluorouracil (5-FU) is an anti-neoplastic drug which is administered in a number of cancers, the clearance of which is mediated by a rate-limiting enzyme dihydropyrimidine dehydrogenase (DPYD)." (PMID 31554517, 2019). "Some research group also reported the suppressed activity due the aberrant methylation of the DPYD promoter region acted as one of the repressors of DPYD expression at transcriptional level and affected sensitivity to 5-FU in cancer cells." (PMID 31105991, 2018). "Considerable variation in 5-FU metabolism and outcome due to the wide range of dihydropyrimidine dehydrogenase (DPD) enzyme activity has been observed and this variability can influence both tolerability and response to cancer chemotherapy." (PMID 21410976, 2011).
cancer (continued). "DPYD promoter methylation was detected in peripheral bloods samples from all (five) DPD-deficient volunteers and in three out of five DPD-deficient cancer patients with a previous history of 5-FU toxicity." (PMID 20809970, 2010). "DPYD encodes dihydropyrimidine dehydrogenase (DPD), an enzyme critical to the metabolism of chemotherapeutic drugs, notably 5‐fluorouracil (5‐FU), which is widely used in the treatment of various cancers." (PMID 40260608, 2025). "In addition to cancer development, miR-27a is acknowledged as a contributing factor to toxicity incidence to fluoropyrimidines via inhibition of DPYD expression." (PMID 39596691, 2024). "This study has shown the absence of the currently known actionable DPYD variants in the Zimbabwean cancer patient cohort." (PMID 37108974, 2023). "Noticeably, the dihydropyrimidine dehydrogenase is of clinical importance in human because deficiency in this enzyme (DPYD in H. sapiens) leads to a severe sensitivity to the administration of 5-fluorouracil, an agent used widely to treat cancer." (PMID 35638108, 2022). "We used a multiple approach, studying DPYD genetic variants, mRNA expression and indirect measuring of DPD activity to try to identify the cause of severe fluoropyrimidine-induced toxicity in a group of cancer patients." (PMID 34442436, 2021). "The study of DPYD gene copy number amplification and corresponding DPYD overexpression may provide a new biological basis for exploring prevention and treatment strategies for 5‐FU‐resistant cancer cells." (PMID 34766149, 2021). "Eight core ADME genes coding for phase I drug metabolism enzymes showed significant associations of their intratumoral expression levels with OS rates in cancers, including dihydropyrimidine dehydrogenase (DPYD) and seven CYP genes (2C19, 2C8, 2C9, 2D6, 2E1, 3A4, 3A5)." (PMID 33202946, 2020). "The aim of this study was to determine whether the five genetic polymorphisms within two genes (DPYD, TYMS) are associated with severe toxicity in patients with cancer receiving fluoropyrimidine-based chemotherapy." (PMID 32695278, 2020). "Some types of cancers exhibited high expression levels of DPYD, and some reports demonstrated that the up-regulation of DPYD in HCC cell lines could decrease the sensitivity to 5-FU, and vice versa." (PMID 26457704, 2015). "Sequence variations in the DPYD gene have been shown to influence the breakdown of the common anticancer drug 5-FU and to provoke severe drug-adverse effects during systemic 5-FU-application in cancer patients." (PMID 19104657, 2008). "Additionally genes DPYD, ABCC1, FTL and ICAM3 whose expression is shown to be associated with outcome of cancer treatment were also observed in the data set." (PMID 18782426, 2008). "With respect to the development of a genetic test, we conducted a systematic analysis of the coding region of the gene DPYD and compared the incidence of commonly found SNPs between cancer patients with good and with poor tolerance of a fluoropyrimidine-based chemotherapy." (PMID 19104657, 2008). "This review highlights the impact of key genes, such as CYP2D6, DPYD, and UGT1A1, which influence the metabolism of essential cancer drugs like tamoxifen, fluoropyrimidines, and irinotecan." (PMID 40149251, 2025). "Using a well-defined drug-gene pair, we identified an enhancer region for dihydropyrimidine dehydrogenase (DPD, DPYD gene) expression that is relevant to the metabolism of the anti-cancer drug 5-fluorouracil (5-FU)." (PMID 37961517, 2024).
cancer (continued). "Dihydropyrimidine dehydrogenase (DPD) is the initial and rate‐limiting enzyme of 5‐fluorouracil (5‐FU), one of the most commonly used drugs to treat cancer." (PMID 37216026, 2023). "Most 5FU is deactivated into fluorodihydrouracil by ubiquitous dihydropyrimidine dehydrogenase (DPD), the rate-limiting enzyme of 5FU catabolism, expressed in various human tissues as well as in human cancer cells." (PMID 28481884, 2017). "Many cancer centers do not offer pharmacogenetic testing outside of indications such as dihydropyrimidine dehydrogenase for fluorouracil toxicity." (PMID 38885448, 2024). "Taken together, these findings indicated that DPYD mRNA expression and DPD protein expression, as well as genomic alterations in DPYD, in cancer cells may be predictive markers of efficacy in 5-FU- and gemcitabine-containing chemotherapy regimens." (PMID 35595780, 2022). "Two highly homologous miRNAs, miR-27a-3p and miR-27b-3p, have been shown to directly reduce the levels of DPYD mRNA and DPD protein in CRC cells, and ectopic expression of miR-27a-3p and miR-27b-3p significantly increased the sensitivity of cancer cells to the cytotoxic effect of 5FU." (PMID 35922756, 2022). "Among the FDA-approved biomarkers for anti-cancer drugs, there are: cytochrome P450 2D6 (CYP2D6) for tamoxifen; rucaparib and dihydropyrimidine dehydrogenase (DPYD/DPD) for fluorouracil and capecitabine; and thiopurine S-methyltransferase (TPMT) for cisplatin, mercaptopurine, and thioguanine." (PMID 35205356, 2022). "Since dihydropyrimidine accumulation was previously shown to control EMT in BC, we tested and demonstrated the hypothesis that high TS enzymatic activity in cancer cells sustains de-differentiation and EMT via a DPYD-dependent pyrimidine catabolism." (PMID 30737477, 2019). "The correlative decrease of DPYD protein to its decrease in mRNA were not so apparent in the liver as it was in cancer cells, something which has previously observed." (PMID 28851987, 2017). "Dihydropyrimidine dehydrogenase (DPD), orotate phosphoribosyltransferase (OPRT) and thymidylate synthase (TS) are enzymes that play key roles in 5-FU metabolism as well as drug resistance in carcinoma cells." (PMID 27612427, 2016). "S-1 (Taiho Pharmaceutical Co., Ltd, Tokyo, Japan) is a dihydropyrimidine dehydrogenase (DPD)-inhibitory fluoropyrimidine (DIF), which showed the highest response rate among many oral anticancer agents against unresectable advanced carcinomas in phase II studies." (PMID 16189518, 2005). "Thus, it may be informative to further investigate the DPYD gene in TE11‐FR cells and their potential resistance to other anti‐cancer drugs, such as cisplatin and docetaxel." (PMID 34042293, 2021).